CD274 (CD274 molecule)
Diseases named in the same sentence as CD274 in open-access papers (continued):
Sharing a sentence is not in itself a finding about the gene and the disease.
lung cancer (continued). "To confirm that BEX2 and CD274 are mutually exclusive in their expression, we tested BEX2 and CD274 protein expression by western blot or flow cytometry using 16 cell lines derived from various cancers, including cholangiocarcinoma, hepatocellular carcinoma, gastric cancer, lung cancer, and glioma." (PMID 33299012, 2020). "In myeloid-derived suppressor cells (MDSCs) of LLC (Lewis Lung Carcinoma) mice, HIF-1α can directly bind to the hypoxia-response element (HRE) in the CD274 promoter, promoting PD-L1 transcription." (PMID 38426097, 2024). "In the lung cancer dataset, the highest AUC was detected for miR-17-5p microRNA, followed by KRAS and CD274 (PD-L1)." (PMID 37568797, 2023). "To further validate our findings in samples from patients with cancer, we first assessed mRNA expression levels of ATXN3 and CD274 in 22 lung cancer patients and found a positive correlation between ATXN3 and CD274 expression." (PMID 38038129, 2023). "Programmed death ligand 1 (PD-L1, also known as CD274) expression has been proposed as one of the pan-cancer biomarkers for immunotherapy including GC, breast cancer, lung cancer, etc.." (PMID 37899172, 2023). "A high expression level of programmed death-ligand 1 (PD-L1, CD274), an essential immune checkpoint protein, is observed in different types of cancers, particularly lung cancer." (PMID 35720000, 2022). "The activation markers GZMB, PRF-1, and IFNγ, migration marker CD183 (CXCR3), and inhibitory marker CD274 (PD-1), were measured and compared in CD8+ T cells with A549 co-cultured, chemokines treated, and patients with late-stage lung cancer." (PMID 34680466, 2021). "With the input of Cluster 1 cytokines, we revealed a distinct cluster of lung cancer samples with the reduced expression of EGFR and CD274." (PMID 34045585, 2021). "PD-L1, also known as B7-H1 and CD274, is continuously expressed in many solid tumors, such as lung cancer, ovarian cancer, and renal cell carcinoma." (PMID 34131111, 2021). "In lung cancer cells, overexpressed MUC1-C increased the occupancy of NF-κB p65 in CD274 promoter, which enhanced CD274 transcription." (PMID 33413496, 2021). "Results showed that the mRNA expression of PD-L1 (CD274) was higher in KRAS-mutant lung cancer cells than in KRAS wide-type (WT) cells, and Western blot analysis showed a higher tendency of PD-L1 protein level in KRAS mutant H441 and H460 cells." (PMID 34073318, 2021). "In the setting of lung cancer, we tested a simplified immune signature using CD8A and CD274 mRNA quantification using RNAseq." (PMID 30744168, 2019). "The development of effective, immune checkpoint inhibitorssuch asPDL-1 (CD274), PD-1 and CTLA-4 has brought to the forefront the importance of the immune system in the treatment of lung cancer." (PMID 28105457, 2016). "To extend our work to additional models of lung cancer MCTS including fibroblasts and macrophages, we selected a cell line expressing a similar level of CD274 than ADCA117, H1437, as well as a cell line expressing higher level of CD274 compared to ADCA117, H1975." (PMID 38581044, 2024). "Moreover, increased CD274, PDCD1, and CTLA4 levels are strongly related to the overexpression of POSTN in lung cancer, especially LUSC." (PMID 35508298, 2022). "This study aimed to identify novel single nucleotide polymorphisms (SNPs) of programmed death-1 (encoded by PDCD1) and its ligands, programmed death ligand 1 (CD274) and 2 (PDCD1LG2), associated with lung cancer risk in never-smoking women." (PMID 34631591, 2021). "Future investigation will show whether IL-10 is involved in the high PD-L1/CD274 expression of monocytes and blood DC subtypes observed in lung cancer patients with a poor therapy response to anti-PD1 therapies." (PMID 33066260, 2020). "DC treated with lung cancer cell culture supernatants significantly downregulated the expression of MHC class II molecules and of the costimulatory molecules CD40 and CD80, but upregulated the inhibitory molecule PD-L1/CD274." (PMID 33066260, 2020).
lung cancer (continued). "Interestingly, PD‐L1/CD274, PD‐L2/PDCDLG2, and IDO1, which belong to the checkpoint pathways, were highly expressed in the brain metastases of lung cancer." (PMID 32017467, 2020). "The aim of our study was to assess the expression of the coinhibitory molecule PD-L1/CD274 on different antigen-presenting cells (monocytes and dendritic cell subsets) in the peripheral blood of 35 patients with nonsmall cell lung cancer undergoing checkpoint inhibitor therapy." (PMID 33066260, 2020). "This review summarizes the hot topics of immunohistochemistry in lung cancer, including (i) adenocarcinoma vs squamous cell carcinoma; (ii) neuroendocrine markers; (iii) ALK, ROS1, and EGFR; (iv) PD-L1 (CD274); (v) lung carcinoma vs malignant mesothelioma; and (vi) NUT carcinoma." (PMID 29538329, 2018). "In lung cancer cells undergoing epithelial–mesenchymal transition (EMT), tumor growth factor-beta 1 (TGF-β1) decreases expression of the DNA methyl-transferase 1 (DNMT1), an enzyme that methylates the CD274 promoter, thus resulting in increased PD-L1 expression." (PMID 33114576, 2020). "It is important to note, however, that the contribution of CD274 expression on non-tumor cells to inhibit the anti-tumor response has at least been questioned and recent studies in pre-clinical lung cancer models also suggested a more dominant role for cancer cell-derived CD274." (PMID 28423491, 2017).
breast cancer (2,416 papers, 2008 to 2026). A primary or metastatic malignant neoplasm involving the breast. "The CD274 ferroptosis-driver score is associated with prognosis and to the risk of recurrence in breast cancer." (PMID 38201582, 2023). "The CD274 ferroptosis-driver score is associated with the prognosis and risk of recurrence in breast cancer." (PMID 38201582, 2023). "In the breast tumor transcriptome, the CD274 ferroptosis-driver score was found associated to the prognosis of breast cancer patients and also to the risk of recurrence (g70, ggi and oncotypeDx scores)." (PMID 38201582, 2023). "The associations between CD274 and ferroptosis-driver expressions were verified to be relevant in the clinic by expression score computing in two independent cohorts of breast cancer (TCGA and METABRIC)." (PMID 38201582, 2023). "It is well known that the expression of PDL1 (also known as CD274) in breast cancer is associated with large tumor size, high grade, and high proliferation." (PMID 35280756, 2022). "In breast cancer, CD274 expression is associated with overall survival." (PMID 38201582, 2023). "MiR-93 has been implicated as a potential immune regulator in breast cancer cells through targeting programmed death-ligand 1 (PD-L1)/cluster of differentiation 274 (CD274), programmed Cell Death 1 Ligand 2 (PDCD1LG2), and natural killer cell cytotoxicity receptor 3 ligand 1 (NCR3LG1)." (PMID 33918859, 2021). "A total of seven CD274/PD-L1 CN gains (0.4%, 7/1918) and five PD-L1 CN deletions (0.3%, 5/1918) were identified, and only one sample originated from primary breast cancer with the HER2 subtype and the other samples were from metastatic sites." (PMID 40182039, 2025). "TWIST1 expression is positively correlated with CD274/PD-L1 expression in metastatic breast cancers and TNBC cell lines." (PMID 38893094, 2024). "In breast cancer, exosomal CD274 from cancer cells suppressed T cell‐mediated killing activity and enhanced tumour growth." (PMID 39051750, 2024). "Collectively, these results suggest that the expression levels of TWIST1 and CD274 (PD-L1) are positively correlated in ER−/HER2−/TWIST1+ breast cancer cells, including the TWIST1-reprogrammed MCF7-TWIST1 cell lines." (PMID 38893094, 2024). "Because TWIST1 expression in breast tumor cells is associated with metastasis, we further analyzed the expression relationship between TWIST1 and CD274 mRNAs in another dataset obtained from metastatic breast cancer samples." (PMID 38893094, 2024). "Case 6 is an adult patient with right-sided breast cancer with positive PD-L1 expression and disruption of the CD274 3' UTR region accompanied by driver gene ERBB2 amplification." (PMID 36717553, 2023). "Basal and TNBC subtypes of breast cancers overexpressed CD274 conjointly with three ferroptosis drivers: TNFAIP3, IFNG and IDO1 (IDO1: inhibitory immune checkpoint)." (PMID 38201582, 2023). "Rb-loss reduces several ‘hallmarks’ of immune response in mouse models, and its deficiency correlates with the induction of PVR, CD274 and several other IC modulators, including ICOSLG and TNFRSF12A in human breast cancer." (PMID 37230983, 2023). "Based on SCRNA-sec, we evaluated the co-expression of the CD274 (encoding the PD-L1 protein) and PDCD1 (encoding the PD1 protein) genes in six breast cancer samples." (PMID 36674951, 2023). "At the protein level, the induction of Cd274 and Tnfaip3 was confirmed in breast cancer stem cells under salinomycin treatment." (PMID 38201582, 2023). "Bioinformatic analysis showed that HK2 expression is associated with upregulated CD274 mRNA expression, reduced infiltration of CD4+ and CD8+ T cells in breast cancer specimens, and decreased survival time of breast cancer patients." (PMID 37377974, 2023). "The independence of the CD274 ferroptosis-driver score in the breast cancer prognosis was investigated through building a multivariable overall survival model on the TCGA transcriptome cohort." (PMID 38201582, 2023).
breast cancer (continued). "This population expressed the immune checkpoint CD274 (PD-L1) and facilitated the expansion of breast cancer mammospheres compared with the adipogenic population." (PMID 36009475, 2022). "During the 2020 ESMO Breast Cancer Virtual Meeting, an increase in the number of PD-L1/CD274 genes measured by CNA was proposed as a predictive marker for PD-L1 inhibitor efficacy." (PMID 35565233, 2022). "The results indicated that IGF2BP3 expression was positively correlated with infiltration of CD8+, CD4+ T cells, and B cells in each of the breast cancer subtypes, which was similar to the effect of PD-L1 (CD274)." (PMID 35197058, 2022). "For example, DUS1L, a gene negatively correlated with CD274, was shown in ovarian, gastric, and breast cancer to be beneficial at high levels of expression." (PMID 34067485, 2021). "The eribulin-resistant MDA-MB-231 breast cancer cell line also showed lower CD274 (PD-L1) expression than the parental cell line." (PMID 34775950, 2021). "This breast cancer model showed an increase in G-MDSCs and PD-L1+ (also known as CD274+) DCs and a decrease in CD8 T cells in tumors from obese mice, making it a clinically relevant model." (PMID 33653826, 2021). "CD274 (PD-L1), which is considered as an adaptive immune resistance marker in basal-like breast cancers, was overexpressed in C3 compared to C2 in internal and external cohorts (P < 0.0001)." (PMID 31101122, 2019). "The findings of a previous study indicated that doxorubicin can downregulate the expression of CD274 on the surface membrane and promote its nucleus translocation in breast cancer cells." (PMID 27855694, 2016). "Our results indicated that CD274 gene was only slightly amplified in a small subset of breast cancer which showed strong protein expression of PD-L1." (PMID 27390646, 2016). "The T-cell inhibitory molecule PD-L1 (B7-H1, CD274) is expressed on tumor cells of a subset of breast cancer patients." (PMID 26245467, 2015). "Furthermore, CD274 was highly expressed in breast cancer cells MCF-7 and MDA-MB-231 compared to normal cells." (PMID 38166842, 2024). "Furthermore, PD-L1 (CD274) protein is expressed at low levels in ER+/HER2−/TWIST1− epithelial breast cancer cell lines, including MCF7, ZR-75-1, and T47D, while it is at high levels in ER−/HER2−/TWIST1+ TNBC cell lines, including MDA-MB-436, BT549 and SUM1315." (PMID 38893094, 2024). "In a breast cancer mouse model, chronic stress or sympathetic stimulation increased inflammation, as measured by M2 macrophage infiltration, and immune invasion through PD-L1 (also known as CD274) expression." (PMID 36621886, 2023). "In an exploratory analysis in patients with advanced breast cancer treated with durvalumab, HR for ICI efficacy with CD274 gain/amplification was 0.18 (95%CI = 0.05–0.71, p = 0.0059), with CD274 normal/loss ICI efficacy HR = 1.12 (95%CI = 0.42–2.99, p = 0.8139)." (PMID 37174086, 2023). "The high expression levels of CD274 and IL8 in basal-like breast cancer were validated by qRT-PCR and western blot, suggesting that clinical CD274- and IL8-targeting therapies may be more suitable for basal-like breast cancer." (PMID 31293831, 2019). "Our findings highlighted several features of claudin-low breast cancer with potential therapeutic implications, including a low tumor mutational burden, high expression of the immune checkpoint gene CD274 (encoding PD-L1), and high expression of PTGS2 (encoding cyclooxygenase-2)." (PMID 31366361, 2019). "As the inhibitors of PD-L1, which is encoded by the CD274 gene, are already in clinical use and the gene product of CD70 is another potentially interesting immunotherapy target, we focused on the CD274:CD70 interaction in the context of IFNγ expression in breast cancer." (PMID 37106127, 2023).
breast cancer (continued). "In addition, the GEPIA web tool analysis showed that the mRNA levels of NFAT1 (NFATC2) were positively correlated with the expression of PD-L1 (CD274) in ccRCC, lung adenocarcinoma, bladder cancer, liver cancer, prostate cancer, pancreatic cancer, and breast cancer." (PMID 35081978, 2022). "Within the context of The Cancer Genome Atlas (TCGA) dataset, expression of CD274 mRNA, which encodes programmed death-ligand 1 (PD-L1), was found to be significantly overexpressed in TNBC patients compared to patients with HER2 + or luminal breast cancer (BC)." (PMID 35717238, 2022). "Furthermore, in breast cancer cells, miR-873 suppressed PD-L1 expression by targeting CD274 mRNA." (PMID 33413496, 2021). "Interestingly, BRCA1-, but not BRCA2-, deficient breast cancer was associated with higher PD-L1 (CD274) expression compared to BRCA-proficient breast cancers in both WSI and TCGA cohorts (PBRCA1 = 5.6 x 10−6 and 0.014, respectively." (PMID 31022191, 2019). "In addition, we used precise stratification of PD-L1 expression on tumor or immune cells of certain breast cancer subtype and suggested that patients with PD-L1 expression in basal-like tumors by immune cells or with CD274 gene copy number gain had a longer disease-specific overall survival." (PMID 27390646, 2016). "We also noted that African ancestry was associated with a higher frequency of copy number alterations in CD274/JAK2/PDCD1LG2 (n = 150; OR = 1.56; FDR = 0.01), which was preferentially found in ER/HER2-negative breast cancer." (PMID 41162424, 2025). "To confirm the stemness and immunomodulation markers expression on mouse breast cancer cell lines, we analyzed the expression of CD44 and CD274 (PD-L1) with flow cytometry in two cell lines, EO771 and 4T1." (PMID 40160820, 2025). "In breast cancer, TET2 recruits HDAC1/2 to remove H3K27ac at the CD274 promoter, thereby repressing its transcription." (PMID 41409271, 2025). "Based on the TCGA database, we identified 119 TNBC patients among 1059 primary breast cancer cases and assessed the prognostic significance of MYC, KRAS, and CD274 (PD‐L1) mRNA expression." (PMID 41020311, 2025). "Our analysis identified elevated levels of immune-relevant proteins, including VTCN1, CD274, and CD73, specifically within the basal-like subtype of breast cancer (BLBC), compared to other subtypes." (PMID 40229283, 2025). "Through the TIMER2.0 database, we found that STAT3 was positively correlated with programmed death‐ligand 1 (PD‐L1, CD274) expression in breast cancer, and this correlation was more pronounced in BRCA‐Basal‐type breast cancer." (PMID 40918170, 2025). "A higher expression of CD274 was found in the TNBC subgroup of the METABRIC cohort, as compared to other breast cancer samples (p-value = 1.25 × 10−10)." (PMID 38201582, 2023). "Analysis of a publicly available human breast cancer data set (METABRIC), demonstrated a small but significant correlation between FERMT1 (Kindlin-1) and CD274 (PD-L1) gene expression." (PMID 36883731, 2023). "An incidence of 0.36% was detected in this cohort, consistent with TCGA (The Cancer Genome Atlas), while the prevalence of SV in CD274 UTR region in liver and breast cancer were significantly higher than TCGA." (PMID 36717553, 2023). "A strong correlation between STAT4 and CD274 was unmasked in clinical single‐cell dataset GSE176078 and TCGA–breast invasive carcinoma (BRCA) cohort, and in breast cancer cell lines." (PMID 38107057, 2023). "On immune checkpoint genes in breast cancers, POGLUT2 was positively correlated with CTLA4, CD274, TIGIT, LAG3, and PDCD1." (PMID 36158688, 2022). "Here, the authors generate a vaccine that integrates CD274 siRNA into the L1 protein of human papillomavirus, which cooperates with ICB by activating innate immunity in breast cancer models." (PMID 32332752, 2020).